TIGIT (T cell immunoreceptor with Ig and ITIM domains)
Diseases named in the same sentence as TIGIT in open-access papers (continued):
Sharing a sentence is not in itself a finding about the gene and the disease.
tumor (continued). "While tumor burden (volumes and weight) were significantly reduced after anti-TIGIT or anti-PD-1 treatment, a further tumor inhibition was observed in mice treated with both anti-TIGIT and anti-PD-1." (PMID 34659197, 2021). "Our datamining showed that TIGIT RNA expression is upregulated in POLEmut tumours which, based on the literature, would indicate worse outcomes." (PMID 34830795, 2021). "Recently Joe-Marc Chauvin reported that dual PD-1/TIGIT blockade potently increases tumor antigen-specific CD8+ T cell expansion and function in vitro and promotes tumor rejection in mouse tumor models." (PMID 33782477, 2021). "Taken together, these data indicate that VV-α-TIGIT has the ability to recruit and activate T cells in the tumor microenvironment and reduce the TIGIT positive immune suppressive T cells." (PMID 33581644, 2021). "In patients with high-grade serous carcinoma, NanoString analysis of tumor tissues has indicated that recurrent tumors acquire a more inflamed phenotype with increased expression of TIGIT, CTLA4, Lag-3, and Tim-3 compared to primary tumors." (PMID 33670993, 2021). "For example, in the tumor microenvironment, TIGIT in tumor-infiltrating lymphocytes is often at a high expression level." (PMID 34631507, 2021). "TIGIT is highly expressed in tumor samples and T cells that also express PD-1, suggesting a role in T cell exhaustion." (PMID 33732652, 2021). "Mouse models have shown that TIGIT/PVR binding induces immune evasion of tumor cells, one of the key hallmarks of cancer." (PMID 33879814, 2021). "Several preclinical mouse models have been used to assess the anti-tumor efficacy of anti-TIGIT blocking mAbs." (PMID 33670993, 2021). "It is known that PD-1 is also expressed on tumor cells, however, TIGIT expression on tumor cells is only described on murine cell lines but not on human cells by now." (PMID 34102454, 2021). "Cox regression model showed that high expression of TIGIT in tumor samples correlates with poor prognosis in KIRC, KIRP, LGG, UVM, and with favorable prognosis in BRCA, CECS, HNSC, SKCM." (PMID 34795387, 2021). "TIGIT inhibits human NK cytotoxicity against the tumor by interacting with CD155 and CD112 and does so by an “alternative self” mechanism by preventing self-killing despite activating DNAM-1 signal." (PMID 34199783, 2021). "Blockade of TIGIT in these mice prevented exhaustion and promoted not only NK cell-dependent tumor immunity, but also tumor-specific T cell function in an NK cell-dependent manner, resulting in prolonged mouse survival." (PMID 33946954, 2021). "Several groups consistently reported that TIGIT expression was elevated on CD8+ tumor infiltrating lymphocytes (TILs) and regulatory T cell (T reg) in a variety of tumors." (PMID 33782477, 2021). "Different tumor models in mice showed that TiNK-cells overexpress TIGIT which is accompanied by an exhausted phenotype." (PMID 34276685, 2021). "This possibility is consistent with a recent study that showed CD226hiCD8+ T cells are required for the efficacy of anti-TIGIT immunotherapy in a tumor model." (PMID 33682797, 2021). "We found that the tumor size in mice administered α-TIGIT was suppressed to a greater extent compared with that in mice administered α-PD-1." (PMID 35069212, 2021). "Studies have shown that blockade of TIGIT restores NK cell exhaustion and promotes NK cell-dependent tumor immunity, enhancing degranulation and IFN-γ production in healthy donor CD56dim NK cells." (PMID 34433460, 2021). "TIGIT is overexpressed on either peripheral T cells and tumor-infiltrating CD8+ and CD4+ T cells in HNSCC patients." (PMID 33804419, 2021). "TIGIT is found as a protein on NK cells, and its activation enhances tumor killing, and the binding of bacteria to TIGIT blocks the anti-tumor activity of NK cells." (PMID 34948234, 2021). "Blockade of TIGIT in vivo reversed the exhaustion of tumor infiltrating NK cells and slowed tumor growth, even in a T cell deficient SCID mouse model." (PMID 33766099, 2021).
tumor (continued). "High expression of TIGIT leads to the exhaustion of CD8+ T cells and NK cells, and its expression is associated with the prognosis of tumor patients." (PMID 34174928, 2021). "In tumor tissue, TIGIT expression on CD8+ T cells and Tregs plays a major role in driving suppression within the TME." (PMID 34948104, 2021). "F. nucleatum avoiding NK-mediated tumor cell lysis via FAP2 interaction with the inhibitory NK-receptor TIGIT." (PMID 33841394, 2021). "In this study, combined blocking of TIGIT and PD-1 showed further tumor control, decreased reduction of key factors in glucose metabolism, and significantly inhibit Akt/mTOR signaling pathway compared with either single blocking in tumor-bearing mice." (PMID 34659197, 2021). "Adoptive transfer experiments in mouse tumor models have even suggested that TIGIT ligation dampens anti-tumor immunity predominantly via regulatory T cells, rather than through a direct effect on TIGIT+CD8+ T cells." (PMID 34367161, 2021). "Further phenotypic dissection of the CD8+TILs from mouse tumor models reveals that an exhausted phenotype is presented with an increased expression of TIGIT, PD-1, Tim-3, Lag-3, CD101, CD38, and eomesodermin (Eomes) in CD226loCD8+TILs." (PMID 33670993, 2021). "Dysregulation of TIGIT allows tumour cells to upregulate CD122 and CD155 and avoid immune-mediated destruction." (PMID 33921181, 2021). "Western blot analysis revealed that phosphorylation of AKT and mTOR in tumor infiltrated TIGIT+ T cells was significantly activated by anti-TIGIT plus anti-PD-1 treatments." (PMID 34659197, 2021). "Plasticity of T cells (defined by higher levels of Tcf1 and lower levels of PD1, CD38, CD101, CD39, and TIGIT) has emerged as a significant factor in their function in vivo in viral and tumor models." (PMID 33320837, 2021). "TIGIT was also highly expressed in MEL04 tumor-infiltrating T cells compared with other co-inhibitory checkpoint molecules such as LAG-3 and TIM-3." (PMID 34795004, 2021). "Among inhibitory immune checkpoint molecules, a unique property of TIGIT blockade is that it enhances not only anti-tumor effector T-cell responses, but also NK-cell responses, and reduces the suppressive capacity of regulatory T cells." (PMID 34367161, 2021). "The antitumor efficacy of TIGIT Ab therapy was further demonstrated in a human colorectal xenograft mice model while co-blockers of TIGIT and PD-1 exhibited synergistic suppressing effects on tumor growth." (PMID 34659197, 2021). "In cancer, the dysregulation of immune checkpoints, such as TIGIT and PD1, is directly associated with tumor progression and enhanced immune evasion." (PMID 34025646, 2021). "Inspired by the combination of anti-PD-1 and anti-CTLA4 in lung cancer, the combination of different checkpoint inhibitors (anti-PD-1, anti-NKG2A and anti-TIGIT) was investigated and synergistic anti-tumor effect was observed in preclinical experiments." (PMID 33262461, 2021). "Previous studies have shown that TIGIT is a checkpoint for NK cells, and blocking TIGIT can prevent NK cell exhaustion and trigger effective anti-tumor immunity." (PMID 33581644, 2021). "We described features shared between the tumour and the peripheral blood, especially the circulating TIGIT+ICOS+ Tregs." (PMID 33917832, 2021). "Given all the information above, it is likely that the immunosuppressive effect of TIGIT leads to the tumor cells survival and escape, influencing the initiation and development of the cancers and the patients’ prognosis." (PMID 34795387, 2021). "The CD47/SIRPα and TIGIT/PVR signaling pathway jointly contribute to the immunosuppressive tumor microenvironment." (PMID 34068552, 2021).
tumor (continued). "CD112R and TIGIT blockade boosted cytokine production by NK cells and improved the tumor-killing effect of trastuzumab." (PMID 34507594, 2021). "TIGIT blockade was shown to enhance human NK cell production of IFN-γ as well as tumor cell killing, especially in the context of CD155 expression." (PMID 34503073, 2021). "Surprisingly, targeting TIGIT not only relieved immunosuppression and enhanced immunity but also inhibited tumor metastasis, providing a double therapeutic benefit." (PMID 35069212, 2021). "Even before the discovery of TIGIT, its ligands were known to be upregulated on the surface of tumor cell surface." (PMID 34572463, 2021). "On the other hand, TIGIT expression was also reported to be upregulated on lymphocytes in tumor microenvironment." (PMID 34572463, 2021). "Sufficient tumor regression by treatment with anti-TIGIT mAbs alone has been reported in different mouse tumor models." (PMID 33670993, 2021). "CD226 promotes cytotoxicity and enhances anti-tumour responses, whereas TIGIT, which outcompetes CD226, negatively regulates anti-tumour responses." (PMID 33995362, 2021). "The bispecific antibody showed high specificity and affinity to primate PD-L1 and TIGIT and had significantly higher anti-tumor activity compared to PD-L1 antibody in mouse models." (PMID 34572463, 2021). "TIGIT was reported to be co-expressed with PD-1 on tumor antigen-specific CD8+ T cells and CD8+ tumor-infiltrating lymphocytes (TILs) in human cancer." (PMID 33721026, 2021). "Third, concerning the fact that TIGIT can be overexpressed in various immune cells, the current study has demonstrated the prognostic value of tumor-infiltrating TIGIT+CD8+ T-cells in patients with solid cancers." (PMID 34638729, 2021). "CD155 expression increased in surviving tumor cells after coculturing with TILs from a responder, which suppressed TIGIT+ T-cell activation." (PMID 34795004, 2021). "Since TIGIT ligands are expressed by FDCs, the immune checkpoint receptor TIGIT plays an important role in tumor-infiltrating T cells." (PMID 34069564, 2021). "Taken together, these results indicated that the combination of TIGIT and PD-1 blockade had a synergistic effect in inhibiting tumor progression compared with TIGIT or PD-1 blockade alone." (PMID 34659197, 2021). "For CD8+ T cells, although the cytotoxic molecules (GZMA, GZMB, NKG7, and PRF1) were highly expressed, a fraction of CD8+ T cells showed positive with exhaustion biomarkers (CTLA4, PDCD‐1, and TIGIT), indicating their tumor‐cytotoxic activity was constrained." (PMID 34185421, 2021). "TIGIT has been investigated in tumor immunology and antibody-drug conjugate (ADC) targeting NECTIN4 also showed provisional anti-tumor efficacy in preclinical studies." (PMID 34611125, 2021). "Combined PD-1/TIGIT blockade resulted also in another mouse HCC model in synergistic inhibition of tumor growth and significantly prolonged mice survival." (PMID 34367161, 2021). "TIGIT is upregulated on dysfunctional CD8+ cells that can especially be found in the tumor microenvironment." (PMID 34276685, 2021). "PVR, the major ligand of TIGIT, plays a pivotal role in multitudinous biological processes, especially the tumor immune escape." (PMID 34068552, 2021). "TIGIT is a central marker of T cell dysfunction and has been shown to be upregulated on human tumor-infiltrating CD8+ T cells (also regulatory T cells and NK cells) in a variety of cancers." (PMID 34112738, 2021). "Here, we showed that TIGIT blockade stimulated anti-tumor cytotoxic T cell (CTL) responses and reduced the immunosuppressive MDSCs in a murine model of GBM." (PMID 34025646, 2021). "The expression of TIGIT and TILs on tumor cells was significantly correlated with poor OS (tumor cells HR = 1.78, 95% CI [1.19–2.65], P = 0.005); tumor infiltrating lymphocytes (TILs) (HR = 1.41, 95% CI [1.09, 1.83], P = 0.009)." (PMID 34888386, 2021).
tumor (continued). "Conversely, in several preclinical models of cancer, the blockade of TIGIT prevented NK cell exhaustion and promoted NK cell-dependent tumor immunity." (PMID 34203391, 2021). "The authors also demonstrated that co-culturing CD8+ T-cells with tumor cells enhanced the expression of TIGIT on their cellular surface." (PMID 33916641, 2021). "Taken together, these data suggest a pronounced isotype advantage of the mIgG2a for the induction of anti-tumor response with anti-TIGIT antibodies." (PMID 33117369, 2020). "The more beneficial outcomes that high survival have been observed in tumor-bearing mice received co-blockade of PD-1 and TIGIT treatment, compared to those treated with single anti-TIGIT mAbs." (PMID 32508809, 2020). "Human NK cells, Tregs, memory T cells, and some CD8+T cells, express TIGIT, while in the TME, tumor-infiltrating NK cells show upregulated TIGIT expression accompanied by decreased DNAM-1 levels." (PMID 32714324, 2020). "Several tumor mice models have shown TIGIT upregulation on CTL and NK cells during tumor progression." (PMID 32117298, 2020). "Because previous publications have reported a reduction of B16F10 tumor take in TIGIT KO mice, we also inoculated TIGIT KO mice with B16F10 cells subcutaneously but did not see anti-tumor response in our TIGIT KO mice." (PMID 33117369, 2020). "Blockade of TIGIT recovered the NK cell function and anti-tumor effector activity, improved memory responses after tumor rechallenge, and elicited tumor-specific T cell immune responses, which were dependent on the presence of NK cells." (PMID 32714324, 2020). "Although the anti-TIGIT on both isotypes demonstrated equal binding to mTIGIT and blocking of mCD155, significant in vivo anti-tumor efficacy was observed only with the anti-TIGIT: mIgG2a antibody and not the anti-TIGIT:mIgG1* antibody." (PMID 33117369, 2020). "TIGIT blockade was proven to synergize with anti-PD-L1 antibody therapy helping memory immunity in tumor rechallenge models." (PMID 33255582, 2020). "Exhausted NK cells from patients with bladder cancer (BC) showed upregulation of TIM-3 and TIGIT in both the periphery and tumor." (PMID 32117298, 2020). "Tumor-associated NK cells also exhibit high expression levels of the checkpoint inhibitory receptor TIGIT, and mAb-mediated blockade of this receptor prevents NK cell exhaustion and elicits potent anti-tumor immunity." (PMID 32013092, 2020). "Another immune-checkpoint molecule, the T cell immunoglobulin and immunoreceptor tyrosine-based inhibitory motif domain (TIGIT), was shown to mediate NK cell exhaustion in cancer, with the blockade of TIGIT restoring the anti-tumour activity of NK cells." (PMID 32493990, 2020). "In this way, TIGIT can indirectly inhibit the priming of tumor-reactive T cells but TIGIT engagement can also directly induce T cell inhibition by blocking T cell activation, proliferation, and acquisition of effector functions." (PMID 33101304, 2020). "TIGIT—which competes with DNAM-1 for binding to CD115—interacts with these receptors resulting in inhibition of NK cell anti-tumor function including impaired granule polarization and IFN-γ production and shows higher binding affinity for CD155 than CD112." (PMID 32532329, 2020). "In the CT26 murine CRC model, inhibiting both TIGIT and PD-1 triggered a tumor rejection and reversed CD8+ T cell exhaustion." (PMID 33167514, 2020). "Improved survival was reported in tumor-bearing mice with dual targeting of PD-1 and TIGIT by enhancing CD8+ T-cell activation." (PMID 32117298, 2020). "Meanwhile, anti-TIGIT antibody was also used for the tumor model, and liothyronine exhibited similar tumor inhibition with the antibodies." (PMID 32894141, 2020). "In another study, it was reported that elevated expression of CTLA-4 and TIGIT genes in human CRC tumor tissues is driven by DNA hypomethylation." (PMID 32760400, 2020).
tumor (continued). "The majority of studies evaluating the role of TIGIT on tumor progression have focused on T cells and shown that TIGIT suppresses activity of T cells." (PMID 33304346, 2020). "Comparing all these studies has yielded a common set of genes such as CTLA4, TNFRSF4, TNFRSF18, TIGIT, ICOS, and CCR8 whose expression is higher in tumor‐associated Treg cells as compared to Treg cells from other tissues." (PMID 32272497, 2020). "The newly identified inhibitory receptor TIGIT serves as a novel and encouraging target to increase the anti-tumor activity of CIK cells." (PMID 32882824, 2020). "In vivo TIGIT signaling blockade improved overall survival by significantly suppressing pre-established B16/F10 tumor growth and metastasis." (PMID 32117298, 2020). "TIGIT was found to be expressed in a variety of immune cells, including NK cells, memory T cells, M2-macrophages (M2), Treg cells, tumor-infiltrating lymphocytes (TILs), and individual immunoregulatory cells (e.g., tumor cells and MSCs)." (PMID 32849489, 2020). "At present, PD-1, TIGIT, and Gal-9 are key immune molecules to mediate the immune escape process of tumor cells." (PMID 32849489, 2020). "We compared the tumor volumes of subcutaneous MC38 tumors on untreated TIGIT KO mice with those on WT mice treated with anti-TIGIT:mIgG2a antibody." (PMID 33117369, 2020). "Augments TIGIT+ T-regs, a unique T-reg subset, leading to active suppression of anti-tumor immune response and T-cell exhaustion." (PMID 32185135, 2020). "CD155 expression positively correlated with TIGIT (p < 0.001), and the proportion of TIGIT-positive patients tended to increase with advanced tumor size, T stage, distant metastasis, and TNM stage." (PMID 33490104, 2020). "Recently, the CD226/TIGIT axis has been identified as an important regulator in anti-tumor and anti-viral T cell responses." (PMID 32983106, 2020). "In a variety of tumor models, it was found that compared with NK cells around tumor, NK cells in tumor core express higher TIGIT, resulting in a significant decrease in anti-cancer factors such as IFN-γ and TNF produced by NK." (PMID 33344447, 2020). "We found that CD155 and TIGIT were overexpressed in PSCCE tissues, CD155 expression correlated positively with TIGIT (p < 0.001) and was significantly associated with tumor size, T stage, distant metastasis, TNM stage, and Ki-67 score." (PMID 33490104, 2020). "Remarkably, blockade of TIGIT can refresh the antitumor immunity of exhausted cytotoxic T lymphocytes (CTLs) and inhibit tumor growth in a preclinical CRC tumor model." (PMID 33419310, 2020). "Here we demonstrate, using mouse tumor models, that TIGIT blocking antibodies with functional Fc binding potential induce effective anti-tumor response." (PMID 33117369, 2020). "The data from the present study identified a potential immunosuppressive effect of TIGIT and PD-1 in MDS, and identified the mechanism of TIGIT and PD-1 in the tumor microenvironment by improving the functions of NK and T cells." (PMID 32903786, 2020). "A promising novel target for NK cell-directed checkpoint therapy is TIGIT, due to its evident role in suppressing NK cell anti-tumor activity." (PMID 33120910, 2020). "When focusing on NK cells, TIGIT has been shown to both contribute to and inhibit tumor progression." (PMID 33304346, 2020). "TIGIT+ CD8+ T cells exhibit low production of cytokines that can be recovered by TIGIT knockdown, suggesting a role for TIGIT in the suppression of T cell anti-tumor responses." (PMID 32764229, 2020). "T cells expressing TIGIT‐28 also significantly reduced tumour burden and lengthened survival in a melanoma xenograft model." (PMID 32544282, 2020). "As with other T lymphocyte checkpoints, in vivo blockade of TIGIT in murine tumor models has been shown to reduce Treg frequency, enhance CD8+ T cell effector function, and improve antitumor immunity." (PMID 32508018, 2020).